STAT3 (signal transducer and activator of transcription 3)
Diseases named in the same sentence as STAT3 in open-access papers (continued):
Sharing a sentence is not in itself a finding about the gene and the disease.
cancer (continued). "To delineate the underlying mechanism of the anti-cancer effect of pimozide on HCC cells, we tested select classical pathways involved in HCC carcinogenesis and found that the STAT3 pathway was significantly suppressed after pimozide treatment." (PMID 26061710, 2017). "Although the JAK/STAT3 signaling pathway is well documented in cancer progression, there are few reports on its physiological significance in the formation of TECs." (PMID 29088816, 2017). "Signaling through STAT3 increases the expression of many genes involved in cancer cell proliferation, survival, migration, invasion, and angiogenesis." (PMID 28856117, 2017). "Activation of STAT3 has been observed in a number of cancers, promoting tumorigenesis and metastasis via transcriptional activation of its target genes." (PMID 28859117, 2017). "In the present study, we provide insight into some part of the mechanism that involves the STAT3-HIF-1α axis on the vanillin-mediated suppression of cancer cell migration and invasion." (PMID 28257048, 2017). "We found that cancer-derived interleukin-6 (IL-6) induces the immunosuppressive ability of MDSCs by activating the STAT3/IDO signaling pathway, but the detailed molecular events are unclear." (PMID 29326716, 2017). "Currently, STAT3 signaling is believed to be one of the signal transduction pathways that is most closely related to the occurrence of malignant tumors." (PMID 27524415, 2017). "Several previously published papers have shown that constitutive activation of STAT3 plays an important role in the development of MDR in cancer cells." (PMID 28027688, 2017). "In conclusion, we provide evidence for the first time that anticancer effect of TTB on diverse cancer cells result from the induction of ROS-mediated apoptosis by inhibiting of STAT3 phosphorylation and enhancing of DNA damage." (PMID 28245605, 2017). "Myeloid compartment specific deficiency in TGF-β receptor II showed lower susceptibility to DSS induced colitis-associated cancer along with lower percentage of F4/80+ TAM infiltration and downregulation of STAT3 phosphorylation in the colonic adenoma tissue." (PMID 28197019, 2017). "Alantolactone has been reported to have anti-inflammatory and anti-cancer effects through IL-6-induced signal transducer and activator of transcription 3 (STAT3) signaling pathway." (PMID 28706484, 2017). "A variety of downstream signaling cascades can be triggered by nicotine through α7 nicotinic receptors, including the Ras/Raf-1/MEK1/ERK and JAK-2/STAT-3 pathways, resulting in the progression of cancer." (PMID 28974241, 2017). "The transcriptional activity of STAT3, an important mediator of cytokine signaling for oncogenesis and cancer cell migration, is mainly depends on post-translational modifications." (PMID 28938568, 2017). "It is known that STAT3 transcriptionally upregulates miR-92a in cancer cells, and the promoter region of the miR-17-92 cluster genes contains a conserved binding site for STAT3." (PMID 29254202, 2017). "One of the cancer cases treated with only radiation therapy showed diffuse and multifocal positivity for STAT3 and 2 cases that were treated with radiation therapy were diffuse and strongly positive for STAT5A." (PMID 29156772, 2017). "Previous reports have shown that activation of STAT3 reduces the apoptotic effect of chemotherapeutic drugs in various cancer cells by up-regulating Bcl-2 and Bcl-xL." (PMID 28114390, 2017). "A previous study indicated that JAK2/STAT3 was involved in the muscle wasting induced by cancer cachexia by regulating the inflammatory response." (PMID 28489606, 2017). "Because of the role of STAT3 in inflammation and cancer development, targeting STAT3 is a rational treatment strategy for CCA." (PMID 29029413, 2017). "Numerous reports showed that SOCS3 defects are responsible for sustained IL-6/STAT3 signaling in human cancers." (PMID 29326716, 2017).
cancer (continued). "Notwithstanding, the prognostic role of p‐STAT3 in cancer patient outcome seems to be conflicting among various solid cancers." (PMID 28084011, 2017). "Oncogenic kinase signaling pathways, including PI3K/Akt and STAT3, are often upregulated in cancer initiation and invasion." (PMID 28903339, 2017). "In cancer cells, the complexes containing STAT3, HIF-1α, CBP/p300, and Ref-1/APE bind to the Vegf promoter and increase VEGF expression." (PMID 28978186, 2017). "In the present study, we evaluated the inhibitory effects of vanillin on hypoxia-inducible factor (HIF)-1α accumulation and cancer cell motility under hypoxia by abrogating STAT3-mediated HIF1A mRNA expression." (PMID 28257048, 2017). "Overall, we conclude that Atn inhibited TNBC growth and invasion and induced cancer cell apoptosis mainly through the inhibition of the STAT3 signal pathway." (PMID 27861147, 2017). "JAK/STAT3 is a major signalling pathway for leptin action and JAK/STAT3 can be a signalling intermediate for EMT via TGFB1 in cancer." (PMID 28542577, 2017). "In this review, we detailed the recent knowledge of SHP-1/STAT3 signaling in cancer progression and potent anti-cancer agents that can target this pathway." (PMID 28594363, 2017). "Both phosphorylated signal transducer and activator of transcription 3(pStat-3) and integrin αvβ6 can play vital role in the development and progression of cancer." (PMID 28061445, 2017). "GYY4137, a hydrogen sulfide (H2S) donor, suppresses STAT3 activation by effectively reducing p-STAT3 levels in cancer cells." (PMID 28978186, 2017). "This directed delivery of siRNA targeting the STAT3 gene (ESTA-MSV/STAT3 siRNA) knocked down STAT3 protein production in nearly 50% of cancer cells in the bone and led to enhanced survival (25% extension of life) in mice bearing MDA-MB-231 bone metastasis." (PMID 28703779, 2017). "The constitutively activation of STAT3 is a point of convergence for numerous oncogenic signaling pathways in cancers." (PMID 28938560, 2017). "Several other chemicals have also shown anti-cancer activity in treating HCC cells through the inhibition of STAT3 signaling." (PMID 26061710, 2017). "Especially considering the significant decrease of miR-218 in ALDH positive cells with cancer stem cell characterics, further investigation of IL-6/STAT3 as a potentially therapeutic target in NSCLC is warranted." (PMID 28830450, 2017). "The important role of STAT3 signaling in carcinogenesis and cancer progression has led to its consideration as a potential molecular target for anti-cancer agents." (PMID 28054986, 2017). "The activation of FAK/Syk/Akt/mTOR and STAT3 pathways contributes to Reelin-induced cancer cell growth and metabolic reprogramming." (PMID 28345605, 2017). "The research advance on the biological information of STAT3 has paved the way for its utilization in cancer therapy." (PMID 28588262, 2017). "There is crosstalk between the two pathways in EMT progression, as EGF treatment enhances IL-6 production, and elevated level of IL-6 is associated with cancer cell aggressiveness and metastasis by inducing EMT through activating STAT3 and Akt signaling." (PMID 28903339, 2017). "Studies have reported signal transducer and activator of transcription 3 (STAT3) is active in many cancers." (PMID 29262638, 2017). "The inhibition of the STAT3 pathway in both cancer and immune cells (particularly myeloid populations) constitutes an important target for cancer therapy, including MM therapy." (PMID 28435516, 2017). "Treatment of TNBC cell lines with pharmacological agents targeting STAT3, revealed this factor to be required for cancer stem cell maintenance and cell survival in TNBC." (PMID 28030809, 2017). "It has been well established that activation of the signal transduction and activator of transcription 3 (STAT3), a key effector protein of IL-6 signaling, is critical in initiating oncogene transcription and cancer progression." (PMID 28077171, 2017).
cancer (continued). "The persistent tyrosine phosphorylation of STAT3 (pY-STAT3) and higher expression of STAT3 are observed in many human cancers and are often correlated with an unfavorable prognosis in these patients." (PMID 29126425, 2017). "In animal models, the association between colitis and cancer (CAC) is linked to NF-κB and STAT3 pathways, which are known to stimulate malignant cell growth and tumor formation." (PMID 28362332, 2017). "An increase in the level of un-phosphorylated STAT3 contributes greatly to the development of cancers by driving EMT." (PMID 28413603, 2017). "The induction of IL-6 secretion and subsequent autocrine/paracrine activation of STAT3 signaling supports the self-renewal activity of not only cancer cells but also embryonic stem cells or induced pluripotent stem cells." (PMID 28099924, 2017). "Some studies have suggested a correlation between autophagy and the cellular localization of STAT3 in human cancer." (PMID 28526807, 2017). "The inhibition of STAT3 and increase in ROS production are antitumor activities that jointly promote cancer cell apoptosis." (PMID 28397855, 2017). "Stat3, an important transcript factor in many human cancers, shows a high level of expression and activation in ABC-DLBCL." (PMID 28069035, 2017). "Stat3 transduces cytokine and growth factor signaling in cells, transcriptionally regulating a diverse array of cellular processes germane to cancer, such as cell proliferation, apoptosis, angiogenesis, immune response and metastasis." (PMID 29190807, 2017). "Given the heterogeneity of TNBC revealed by molecular profiling, the general applicability of STAT3 signaling in cancer cells provides an alternative strategy to traditional chemotherapy." (PMID 28084011, 2017). "Persistent activation of STAT3 in prostate carcinomas has been correlated with the shortened survival of cancer patients." (PMID 28077171, 2017). "Altogether, this data describes a complex relationship between STAT1 and STAT3 signaling in cancer that should be considered when developing STAT-targeting compounds." (PMID 28636670, 2017). "Our findings further suggest that acetylation of STAT3 (K685) is a novel therapeutic target to treat human cancers." (PMID 29137356, 2017). "More recently, it has been demonstrated that HCV NS4B induces the production of reactive oxygen species (ROS) via the endoplasmic reticulum overload response (EOR)-mediated cancer-related STAT3 pathway." (PMID 28443075, 2017). "Previous studies have found that during cancer‐induced inflammation, STAT3 collaborates with other transcription factors such as NF‐κB, also a well‐known inducer of the cachectic phenotype." (PMID 28264935, 2017). "Specifically, we engineered MFs to be assembled of synergistic CpG and Stat3-silencing shRNA, such that TLR9 and STAT3 signaling pathways were synergistically leveraged to elicit potent immunostimulation in APCs for cancer immunotherapy." (PMID 29133898, 2017). "Both Src and JAK2 are the upstream tyrosine kinases of STAT3, and they have been found to be constitutively phosphorylated/activated in various cancers including CRC." (PMID 28503147, 2017). "Stat3 is a transcription factor that promotes the progression of urothelial cells from carcinoma in situ to invasive bladder cancer." (PMID 29190807, 2017). "Blockade of TGF-β as well as JAK2/STAT3 signaling reduced the proliferation and cytokine production of both cancer cells and MFs in culture." (PMID 28819126, 2017). "STAT3 signaling has also been identified to promote the progression and metastasis via inducing cancer stem cell-like properties and chemotherapeutic resistance in different cancers." (PMID 28591704, 2017). "This process has been reported to induce JAK2/STAT3 phosphorylation and can contribute to cancer cell survival." (PMID 28894215, 2017).
cancer (continued). "CA10 induced ROS generation and subsequent activation of endoplasmic reticulum (ER) stress and inhibition of signal transducer and activator of transcription 3 (STAT3) phosphorylation, inhibits cancer cell proliferation." (PMID 29254150, 2017). "The compounds (designated 4a, 4b and B9 respectively) were shown to impact the proliferation rate, viability and the motility of cancer cells with constitutively phosphorylated STAT3." (PMID 28636670, 2017). "STAT3 signalling analysis showed that the phosphorylation of STAT3 at Tyr705 was decreased in the cancer group from day 1, and STAT3 phosphorylation at Ser727 was also reduced, indicating that STAT3 signalling was blocked." (PMID 28350008, 2017). "Recently the same group further explored the role of STAT3 in myeloid cells establishing cancer favoring microenvironment." (PMID 28197019, 2017). "The STAT3 signaling cascade is frequently activated in cancer cells and results in enhanced resistance of these cells to apoptosis through multiple mechanisms." (PMID 28720093, 2017). "Further, it should be emphasized that STAT3 signaling is crucial for the regulation of cancer stem cells in a similar way as for the regulation of ES cells." (PMID 28819544, 2017). "While there are a few reports on the inhibitory effects of silibinin on STAT3 pathway in cancer cells, to our knowledge the effects of silibinin on STAT3 and MDR in drug-resistant cancer cells harbouring hyperactive STAT3 have not been reported before." (PMID 28027688, 2017). "This recalls the emerging role for STAT3 and AR in cancer stemness and the overlap in NANOG binding sites with a subset of ARBSs." (PMID 28826481, 2017). "In summary, the present findings demonstrated that HBx-ΔC1 plays a critical role in HCC development and progression via the regulation of cancer stemness, which involves the preferential activation of the Stat3-Nanog pathway." (PMID 28186991, 2017). "Enhanced activity of STAT3 has been observed in a wide variety of human tumors, as a means for the cancer cells to escape therapeutic insult, and survive." (PMID 28859117, 2017). "SHP-1 was shown to be a regulator of STAT3 mediated signaling pathways and is currently under investigation as a target for cancer therapy." (PMID 28674449, 2017). "A number of compounds that inhibit the activity or function of STAT3 have been developed for use in cancer treatment and prevention." (PMID 29207645, 2017). "We previously found that cancer-derived IL-6 induces T cell suppression of MDSCs in vitro via the activation of STAT3/IDO signaling pathway." (PMID 29326716, 2017). "Inhibition of STAT3 signaling has shown a striking ability to inhibit cancer cell growth and therefore, STAT3 has become a promising target for anti-cancer drug development." (PMID 28636670, 2017). "Studies have reported that STAT3 interacts with the Skp2 pathway to regulate the motility and invasion of cancer cells." (PMID 29207614, 2017). "IL-6 and its downstream molecules, such as STAT3, play an essential role in inflammation, aberrant immunity, and also carcinogenesis in some carcinomas." (PMID 28507278, 2017). "In HepG2 carcinoma cells, for example, STAT3 binds directly to CDC25a promoter and activates its expression." (PMID 28222105, 2017). "The activity of Signal Transducer and Activator of Transcription 3 (STAT3) is widely known to play a crucial role in the tumorigenesis of multiple different cancers." (PMID 26799670, 2016). "In our study, intensive immunoreactivity of iNOS was detected in the cytoplasm of cancer cells, and EGFR and phosphorylated STAT3 were strongly expressed in cancer cells of NPC patients." (PMID 28050219, 2016). "SFN was reported to inhibit IL-6-induced as well as constitutive STAT3 activity in a number of cancer cell lines." (PMID 27304884, 2016). "This is the first to demonstrate that STAT3-MMP-9 pathway was partially responsible for macrophage AEG-1-induced cancer cell invasion." (PMID 27793010, 2016).
cancer (continued). "Subsequent western blotting revealed that levels of K685-acetylated STAT3 were higher in the mitochondria of cancer tissue sections than in normal tissue sections." (PMID 28004755, 2016). "By treating cancer cells with exogenous IL-6, we confirmed that IL-6 promotes cell invasion by stimulating the STAT3/Bcl-XL pathway." (PMID 26895473, 2016). "The crucial role of STAT3 in cancer progression and tumorigenesis makes STAT3 a viable molecular target for cancer therapy." (PMID 26883202, 2016). "STAT3 can be activated in cancer cells by multiple cytokines and growth factors, best known for IL-6 and its family members." (PMID 31051015, 2016). "Signal transducer and activator of transcription-3 is a downstream effector of multiple cytokines and growth factors that modulate NK cell activity and also drives tumorigenesis and resistance of cancer cells to therapy." (PMID 27148255, 2016). "Using qRT-PCR analysis, we confirmed these upregulated STAT3 targets in OLA1P2-silenced cancer cell lines." (PMID 26898989, 2016). "Ectopic STAT3 expression clearly increased the mRNA expression of mesenchymal markers including Vimentin and N-cadherin, and decreased the expression of epithelial marker E-cadherin in MCF7 and T47D cells, suggesting that STAT3 promotes EMT in cancer cells." (PMID 26716902, 2016). "RNA FISH technology combined with immunofluorescence analysis confirmed the co-localization of lncRNA OLA1P2 and phosphorylated STAT3 (Tyr705) protein in the cancer cells." (PMID 26898989, 2016). "Cucurbitacin-I (Cu-I, also known as Elatericin B or JSI-124) is developed to inhibit constitutive and abnormal activation of STAT3 in many cancers, demonstrating a potent anticancer activity by targeting disruption of STAT3 function." (PMID 26890145, 2016). "After stimulating cancer cells with conditioned fibroblast media, the level of phosphorylated STAT3, AKT and ERK were observed to increase noticeably in the TFK-1 cell line." (PMID 27206490, 2016). "HCCR expression affected cell growth by regulating apoptosis in the cancer cells, and it had a positive correlation with p-STAT3 expression." (PMID 27052330, 2016). "Bcl-2, Bcl-xL, and Mcl-1, antiapoptotic Bcl-2 family proteins, are highly expressed in human cancer through the enhanced binding of transcription factor STAT3 dimer at their promoter regions." (PMID 26194866, 2016). "Immunohistochemical analyses showed that K685-acetylated STAT3 was widely distributed in cytoplasmic regions in cancer sections obtained from both non-small cell adenocarcinoma and squamous carcinoma lung cancer patients." (PMID 28004755, 2016). "Signal Transducer and Activator of Transcription 3 (STAT3) protein, a cytosolic protein, has been identified as a key regulator of human cancers, contributing to uncontrolled differentiation, proliferation, survival, and tumorigenesis." (PMID 26942696, 2016). "Among the 7 members of the family, STAT3 is the one most commonly constitutively activated in several cancers, including GBM." (PMID 27163161, 2016). "The collaboration and crosstalk of STAT3 and NF-κB play pivotal roles in the pathogenesis of various cancers." (PMID 27602766, 2016). "STAT3 constitutive activation is found in various human cancers and several STAT3 inhibitors have been shown to act as effective cancer cures in preclinical studies." (PMID 27521216, 2016). "In particular, STAT3 is known to promote cell proliferation and angiogenesis and to play a role in the invasiveness and metastatic potential of cancers." (PMID 27052330, 2016). "Since now, the PI3K/AKT, RAS-RAF-MAPK, and STAT3 signaling pathway were identified as a regulatory axis in the resistance to trastuzumab in HER2-positive cancers." (PMID 27581375, 2016). "This downstream modulation of several p-STAT3-driven genes that contribute to cancer progression demonstrates that even modest changes in the activity of surface receptors due to altered glycosylation have potential therapeutic benefit." (PMID 27613843, 2016).